C3 (complement C3)
Diseases named in the same sentence as C3 in open-access papers (continued):
Sharing a sentence is not in itself a finding about the gene and the disease.
fibrosis (17 papers, 2016 to 2025). the formation of excess fibrous connective tissue in an organ or tissue in a reparative or reactive process. "In conclusion, in this phase 2b study, the collagen formation marker Pro-C3 correlated with fibrosis stage, and Pro-C3 and ELF identified advanced fibrosis and cirrhosis and predicted PSC-related events and fibrosis progression." (PMID 38967589, 2024). "The reduction in C3 expression was associated with reduced α-SMA expression and decreased tubulointerstitial fibrosis measured by Masson's trichrome staining." (PMID 30405606, 2018). "The ADAPT algorithm has an area under the receiver-operating characteristics curve of 0.87 for advanced fibrosis and incorporates age, T2DM, Pro-C3, and platelet count." (PMID 38967907, 2024). "The collagen formation marker Pro-C3 was shown to correlate with the fibrosis stage, and Pro-C3 and ELF had utility for identifying advanced fibrosis and cirrhosis and predicting PSC-related events and fibrosis progression." (PMID 38967589, 2024). "Serum Pro-C3, cleaved during collagen III deposition, is a circulating marker of fibrogenesis that progressively increase with fibrosis stage and NAFLD activity score (NAS)." (PMID 35334864, 2022). "Therefore, we inferred that C3 AGT + Fibroblasts are more sensitive and active than other fibroblast subpopulations for the progression of cardiomyopathy as well as fibrosis." (PMID 38799173, 2024). "PIIINP levels alone represent a good diagnostic biomarker for fibrosis, but it has been demonstrated that Pro-C3 (the PIIINP neo-epitope) reflects the effective production of collagen III biosynthesis; furthermore, the increase of serum Pro-C3 levels is correlated with NASH and fibrosis." (PMID 34769333, 2021). "Median baseline levels of Pro-C3, propeptide of type IV collagen, C3M, ELF score, and its components were higher in patients with than without cirrhosis at baseline (Ishak fibrosis stages 5–6 vs. 0–4)." (PMID 38967589, 2024).
prion disease (17 papers, 2013 to 2024). A transmissible disease that is caused by a protein that is able to induce abnormal folding of normal cellular proteins, leading to characteristic spongiform brain changes, which are associated with neuronal loss without an inflammatory response. "Hartmann and colleagues showed that the abolishment of C3+ astrocytes in mice deficient in TNFα, interleukin‐1α and complement component C1qa coincided with accelerated CNS prion disease." (PMID 35852018, 2022). "Reactive astrocytes including those associated with prion diseases upregulate expression of IL-33 and C3, which are known to drive microglia-mediated synapse engulfment and elimination." (PMID 34359897, 2021). "This protective role for microglial C1qa and TNFα in prion disease in the CNS contrasts with the facilitative role observed for C1qa, C3, and TNFα in peripheral prion pathogenesis." (PMID 38786054, 2024). "This phenomenon appears to be unique to prion disease, as inhibition of C1qa and C3 has shown to be neuroprotective in animal models of other neurodegenerative diseases." (PMID 38786054, 2024). "Investigation into both prion disease mouse models and human disease samples confirmed the abundant presence of not only C3 + reactive astrocytes, but also C3 + PrPSc + astrocytes." (PMID 36915214, 2023). "Although the deposition of misfolded PrPSc was unchanged, we found that knockout of TNF-α, IL-1α and C1qa with the abolishment of C3+-astrocyte formation let to a significant acceleration of the prion disease course." (PMID 31118110, 2019). "Our data rather exclude the abolishment of C3+-astrocytes as a therapeutic strategy in prion diseases." (PMID 31118110, 2019). "Although C3+-PrPSc-specific-astrocytes are abundant in human and mouse prion diseases, abolishment of their formation led to an acceleration of prion disease progression." (PMID 31118110, 2019). "Further studies are required to determine whether microglia are required for induction of complement component C3+ reactive astrocytes during prion disease." (PMID 33023255, 2020). "They showed that C3 immunopositive, A1 astrocytes were abundant in the brains of mouse models of prion disease but that surprisingly their abolishment led to an accelerated disease process, possibly by interfering with microglial functioning that was otherwise slowing the disease progression." (PMID 32751955, 2020). "Using specific antibodies, we could show that C3+-astrocytes are highly abundant in a prion disease mouse model and in human sCJD." (PMID 31118110, 2019). "We show that C3+-astrocytes are highly abundant in prion diseases." (PMID 31118110, 2019). "Detailed characterization of the astrocyte activation signature in thalamus tissue showed that astrocytes in prion diseases are highly activated, showing a mixed phenotype that is distinct from other neurodegenerative diseases and were therefore termed C3+-PrPSc-reactive-astrocytes." (PMID 31118110, 2019). "However, independent studies have shown that deficiency in complement component C3 does not affect the development of CNS prion disease, and TNFα was undetectable in the brains of prion‐infected Csf1rΔFIRE mice." (PMID 35852018, 2022). "Since astrocyte polarization profiles have never been investigated in prion diseases, we performed several analyses and could show that C3+-PrPSc-reactive-astrocytes, which may represent a subtype of A1-astrocytes, are highly abundant in prion disease mouse models and human prion diseases." (PMID 31118110, 2019). "Numerous inflammatory (C3+ or GBP2+) astrocytes can be found in tissues of both murine prion disease and human CJD cases, and expression of C3 and GBP2 is significantly upregulated in CJD brain tissue and is associated with disease duration and risk genotype." (PMID 34539348, 2021). "Surprisingly, abolishment of C3+-astrocyte formation by knocking out TNF-α, IL-1α and C1qa accelerated the prion disease course." (PMID 31118110, 2019).
prion disease (continued). "Although the reactive astrocytes in the prion disease-affected brain have been suggested to be neurotoxic, they display a mixed A1 and A2 transcriptomic signature and notably express high levels of CD44 and complement component C3." (PMID 33023255, 2020). "Nevertheless, the role of C1q and C3 in sporadic prion disease or diseases transmitted via the IC route is not clear." (PMID 27609323, 2016). "Though complement components C3 and C5 are not required for prion pathogenesis, the G protein-coupled receptors C3aR1 and C5aR1 might influence prion disease by interacting with other unidentified ligands to elicit a response." (PMID 30596651, 2018). "We have previously shown that a number of typical acute phase proteins serum amyloid A, complement C3, pentraxin 3, and α2-antiplasmin are induced in the brain of animals with prion disease, but there is no induction of message in the liver despite the presence of systemic deposition of PrPSc." (PMID 24366862, 2014).
pulmonary fibrosis (17 papers, 2016 to 2026). Chronic progressive interstitial lung disorder characterized by the replacement of the lung tissue by connective tissue, leading to progressive dyspnea, respiratory failure, or right heart failure. "Both complement system and MUC5B are implicated in host defense and this MUC5B variant is associated with higher C3 gene expression in lung tissue further indicating role of complement system in pulmonary fibrosis progression." (PMID 32385381, 2020). "Increased C3 expression in IPF leads to activation of the TGF‐β/SMAD pathway, which ultimately causes lung fibrosis." (PMID 38018577, 2023). "It has been recently proposed that IL-17A induces protein and mRNA regulation of C3, and limiting complement activation by neutralising IL-17A is a potential mechanism for ameliorating pulmonary fibrosis." (PMID 36605203, 2022). "Interestingly, Arg1, C3, and Ccl17 are all genes considered to be biomarkers of alternatively activated macrophages, a cell type that requires Th2-regulated cytokines for its differentiation, and that also have been implicated in the progression of pulmonary fibrosis." (PMID 27169501, 2016). "Therefore, TGF-β, despite causing pulmonary fibrosis in IPF, can prevent inflammation and pulmonary fibrosis in patients by reducing C3 production." (PMID 37422662, 2023). "This study aimed to investigate the expression of immunoglobulins (IgG, IgM, IgA) and complement component 3 (C3) in the lungs of patients with DM-ILD and those with idiopathic pulmonary fibrosis (IPF) as control." (PMID 36934274, 2023).
tauopathy (17 papers, 2019 to 2025). Neurodegenerative disorders involving deposition of abnormal tau protein isoforms (tau proteins) in neurons and glial cells in the brain. "Ablation of C3aR or C3 in mouse models of tauopathy reversed neuronal loss and neurodegeneration, alongside reduced numbers of GFAP-reactive hypertrophied astrocytes being apparent upon C3aR knockout." (PMID 33071951, 2020). "Similar findings have emerged from recent studies in P301S tauopathy mice, which show neuronal tau accumulation and involvement of classical and alternative complement pathways in synapse loss, with deficiency or inhibition of C1q or C3 being protective." (PMID 40420510, 2025). "In particular, complement component 3 (C3), the strongest upregulated gene in both late phenotype changes and AD maturation, is a major component of the complement cascade, and deficiency of C3 mitigates neurodegeneration and neuronal loss in the P301S tauopathy mouse model." (PMID 36639689, 2023). "Neuroinflammation play an important role in patient with AD and other primary tauopathy diseases as well as in animal models of tauopathy, featured by disease associated with microglia activation, reactive astrocytes, and activated cytokines such as complement C3 and interleukin-3." (PMID 35082657, 2021). "In particular, increases in expression of complement component 3 (C3) and the C3a receptor (C3aR) correlate with disease severity, and deletion of C3aR in tauopathy mice attenuated pathology and normalized the DAM transcriptional signature." (PMID 40113250, 2025). "The mRNA expression of C3 and its receptor C3aR are upregulated in AD patients with tauopathy, and C3aR ablation attenuates tau pathology and reverses neuroinflammation in a tau-transgenic mouse AD model." (PMID 37759245, 2023). "In tauopathy, inactivation of C3-C3aR signaling reverses the deregulation of the immune network and rescues behavior deficits in PS19 mice." (PMID 35413950, 2022). "Given our results indicating significantly increased expression of complement component C3 with TIA1 reduction, we next investigated effects of TIA1 haploinsufficiency and TIA1 knockout on synapse loss in tauopathy." (PMID 32327969, 2020). "In tauopathy the complement factors C1q and C3 are increased in the neural parenchyma and CSF of human AD subjects and in the neural parenchyma of mouse models of AD." (PMID 32327969, 2020).
colitis (16 papers, 2013 to 2025). Inflammation of the colon. "Genes such as C3, Ccl2, Cxcl1, Ifi44, Lcn2, S100a8, and Tnf were strongly induced during colitis, mirroring previously reported inflammation-associated transcriptional responses." (PMID 40806068, 2025). "Mice deficient in C3 or Factor B were protected from acute colitis induction 5 days post DSS treatment and exhibited improved clinical outcome." (PMID 33692968, 2021). "To determine whether reduced colitis associated with colonization by the Δwzy mutant depends on C3, we depleted C3 in WT B6 mice by intraperitoneal administration of cobra venom factor (CVF)." (PMID 33027280, 2020). "Importantly, the ability of the wzy mutant to protect from colitis was blocked by depletion of complement C3 which was associated with impaired intestinal eradication of AIEC in colitic mice." (PMID 33027280, 2020). "In mouse models of dextran sodium sulfate–induced (DSS-induced) colitis, C3 expression and protein production by IECs are markedly increased." (PMID 41031883, 2025). "Recently, single-cell spatial transcriptomics combined with multiplexed error-robust fluorescence in situ hybridization (MERFISH) identified fibroblast subsets with high C3 expression in both healthy and inflamed tissues in murine colitis models." (PMID 41031883, 2025). "Complement activation also contributed to the development of colitis-associated colorectal cancer (CAC), supported by tumor repression in complement deficient mice (C3, C5, or C5aR)." (PMID 33692968, 2021). "To determine if C3 mediates the protective role of the Δwzy mutant against colitis by regulating bacterial numbers, we assessed the colonization levels of the Δwzy mutant bacterium over time after DSS treatment." (PMID 33027280, 2020). "Furthermore, C5–/–, C1q–/–, MBL–/–, C3–/–, fB–/–, and C6–/– mice all show increased susceptibility to acute and chronic DSS-induced colitis, further highlighting the important role of the complement system in the regulation of intestinal immune responses." (PMID 41031890, 2025). "Furthermore, N-acetylspermidine-induced α1,2-fucosylation enhancement facilitated the membrane localization of ZO-1 and ZO-2, while suppressing C3 secretion, both of which contributed to colitis alleviation." (PMID 40776401, 2025). "Interestingly, colonization by the wzy mutant (which lacks LPS) alleviates DSS-induced colitis in a C3-dependent manner, suggesting context-dependent roles for complement in inflammation and microbial control." (PMID 41031883, 2025). "Finally, C3 and Tyrobp were also revealed as colitis-specific hub genes, which is in line with published reports." (PMID 36901742, 2023). "C3 deposition has been observed on commensal bacteria from the gastrointestinal lumen, and C3b has been observed coating the apical membrane of the distal colon in a model of induced colitis, indicating that the complement is activated in the gastrointestinal tract." (PMID 34806406, 2022). "Moreover, C3 was found to be up-regulated in intestinal epithelial cells in the DSS-induced colitis model, and its ablation promoted inflammatory responses in the mid colon and significantly reinforced DSS-induced colitis in C3 knockout mice compared with wild-type littermates." (PMID 36901742, 2023). "Thus, E. coli isolated from colitis tissues may be sensitive to an unknown C3-dependent complement-mediated killing pathway." (PMID 32879431, 2020). "In this study, we found that C3 and S100A10 protein expression were reduced in colon of DSS-induced colitis mice, which were lower in that of CSE knockout mice." (PMID 36189321, 2022). "In chronic dextran sulphate sodium (DSS)-induced colitis, C1q−/−/ MBL−/− mice died at the beginning of the experiment, while C5aR1−/− or C3−/− mice displayed stronger intestinal inflammation and decreased survival rates in comparison to wild type mice." (PMID 30669641, 2019).
colitis (continued). "The treatment with 0.05% DSS for 3 h, the amount of time required to induce morphological changes related to colitis, induces a sixfold increase of VCBP-C and a weak but significant increase in the expression of C3 and IL-17-1." (PMID 29222175, 2018). "Finally, the expression of the revealed hub genes related to acute colitis (C3, Tyrobp, Mmp3, Mmp9, Timp1) and CAC (Timp1, Adam8, Mmp7, Mmp13) was validated by qRT-PCR in the colon tissue of mice with acute colitis and colitis-driven adenomas." (PMID 36901742, 2023). "Still, colitis exacerbated the decrease of GFAP, C3, and S100A10 protein expression." (PMID 36189321, 2022). "In addition, colitis-induced decreases in GFAP, C3 protein, and S100A10 expression were more significant in CSE KO mice than in WT mice." (PMID 36189321, 2022). "Additionally, data presented in the current study reveal the analysis of fecal C3 level as a potentially novel screening method to further discriminate between CD and UC or between CD and non-IBD colitis, independently of status or localization of the disease." (PMID 30669641, 2019).
dengue (16 papers, 2009 to 2025). "Further supporting the association of the AP regulatory proteins with dengue disease severity, levels of C3 levels and factor H were higly correlated." (PMID 19707565, 2009). "Early studies examining the relationship between complement activation and dengue severity demonstrated greater rates of C3 and C1q consumption in severe dengue than in mild dengue, suggesting a role for the complement system driving dengue pathogenesis." (PMID 40294026, 2025). "Decreased levels of C3 and increased levels of anaphylatoxins are correlated with the severity of dengue." (PMID 35204727, 2022). "During a second heterotypic dengue infection, the circulating DENV antigens and anamnestic IgG dengue antibodies activate complement resulting in a reduced level of C3 and increased levels of C3a and C5a anaphylatoxins." (PMID 32751561, 2020). "During a second heterotypic dengue infection, the simultaneous circulation of anamnestic IgG dengue antibodies and dengue viral antigens activates complement via the C3 activator and by initiating the C1, C4, C2 cascade, contributing to a reduced level of C3." (PMID 26918141, 2015). "The levels of C3, C3a, and C5a that we have measured in dengue patients demonstrated the presence of increased complement activity in DHF patients; these findings are consistent with the levels that have been previously reported in patients with this severe form of disease." (PMID 19707565, 2009). "The authors observed a correlation between levels of C3 with the levels of factor B and C4 and based on these correlations the authors demonstrated the direct involvement of both the classical and the alternative pathways in dengue severity." (PMID 19707565, 2009). "A hallmark of severe dengue disease is the presence of elevated levels of cytokines and chemokines including IP-10, ITAC, IL-1β, IL-2, IL-6, IL-8, IL-10, IL-12, IL-13, TNFα, IFNα, IFNγ, MIF, RANTES, histamine, and complement proteins C3, C3a, and C5a within blood and tissues." (PMID 22952474, 2012). "The increased consumption of C3 and elevated levels of byproducts of complement activation (C3a and C5a) that we observed in DHF patients confirmed that higher complement activation is correlated with dengue severity." (PMID 19707565, 2009). "However, the C3 levels in DHF patients (1.0+/−0.6 mg/mL) were significantly (p = 0.002) lower than those in the DF patients during acute dengue infection and also significantly (p = 0.0006) lower than the C3 levels in the healthy control group." (PMID 19707565, 2009). "DHF patients show a decrease in C3 levels compared to dengue patients without hemorrhagic fever (DF) or controls." (PMID 35204727, 2022). "C3 levels have previously been shown to be reduced in severe dengue, and are lower in patients with DHF compared to DF." (PMID 33410734, 2021).